MMP2 (matrix metallopeptidase 2)
Diseases named in the same sentence as MMP2 in open-access papers (continued):
Sharing a sentence is not in itself a finding about the gene and the disease.
bladder cancer (continued). "Our previous studies have shown that FOXO1 and MMP2 are targeted by the anticancer compound ISO for its suppression of bladder cancer invasion." (PMID 36293387, 2022). "In a metastatic xenograft animal study, FXR overexpression suppressed bladder cancer lung metastasis by decreasing matrix metalloproteinase-2 (MMP2), SREBP2 and HMGCR expression." (PMID 36139556, 2022). "There were 7 associations graded as moderate associations for cancer risk, including MMP-2 rs243865 with LC risk and PCa risk, MMP-7 rs11568818 with bladder cancer risk, and MMP-9 rs3918242 with BC risk and oral cancer risk." (PMID 35574300, 2022). "Upregulation of MMP2 is a significant process in the invasion and migration of bladder cancer cells." (PMID 36430344, 2022). "Aberrant regulation of MMP-2 and -9 has been found during malignant transformation, and further progression of invasive types of bladder cancer and several other neoplasms." (PMID 35010907, 2021). "Our results show that GSPs inhibit the migration, invasion, and MMP-2/9 secretion of both T24 and 5637 bladder cancer cells." (PMID 34354794, 2021). "Previous reports showed that miR-146b-5p was involved in developing multiple human cancers, such as nasopharyngeal carcinoma and bladder cancer, targeting functional genes, such as MMP2 and ETS2." (PMID 34332611, 2021). "Gelatin zymography was performed in order to investigate invasiveness through matrix metalloproteinase 2 (MMP-2) activity from bladder cancer cells-secreted media of different WWOX/AP-2α/AP-2γ phenotype." (PMID 33718178, 2021). "In bladder cancer, it is usually upregulated, and this event is correlated with the inhibitory effect on the invasion of bladder cancer that resulted from the reduction of the matrix metalloproteinase MMP2 expression." (PMID 33806327, 2021). "Capsaicin markedly inhibited cell migration through the suppression of SIRT1 deacetylase via proteasome-mediated protein degradation, thereby elevating β-catenin acetylation and decreasing MMP-9 and MMP-2 activation in T24 bladder cancer cells." (PMID 33996570, 2021). "Previous studies showed that MMP-2 and MMP9 are associated with a high stage and grade of bladder cancer." (PMID 33923108, 2021). "Studies in human beings document an association between increased urinary activities of MMP‐2 and MMP‐9 and early‐stage bladder carcinoma." (PMID 32468592, 2020). "Authors also mentioned that, for bladder cancer patients, the elevated levels of MMP-2 were found in bladder tissue samples." (PMID 32751899, 2020). "CCL21/CCR7 enhanced bladder cancer cell proliferation and facilitated migration and invasion by increasing levels of MMP-2 and MMP-9." (PMID 33146700, 2020). "At the same time, in the bladder cancer model, CCL18 causes an increase in the production of VEGF-C and matrix metalloproteinase-2 (MMP-2), which are factors involved in lymphangiogenesis." (PMID 33114763, 2020). "TRPV2 activation was also shown to promote bladder cancer cell metastasis via either matrix metalloproteinase-2- (MMP-2-) or adrenomedullin-dependent mechanisms in the human bladder carcinoma cell line T24/83." (PMID 33376561, 2020). "Future studies should therefore examine the role and function of MMP-2 in SPHF-induced inhibition of bladder cancer metastasis." (PMID 32708058, 2020). "A relationship between MMP-2 expression and stromal support, angiogenesis, invasiveness, and tumor growth was demonstrated using an MMP-2-specific inhibitor in a mouse model of bladder cancer." (PMID 31921634, 2019). "Our previous studies have demonstrated that XIAP promotes bladder cancer metastasis through upregulating RhoGDIβ/MMP-2 pathway." (PMID 31240993, 2019). "Our newly research reported that XIAP promotes bladder cancer metastasis through upregulating RhoGDIβ/MMP-2 pathway." (PMID 31240993, 2019). "Past findings have implicated MK2 in mediating tumor invasion via regulating mRNA stability of MMP-2/9 in bladder cancer." (PMID 30850014, 2019).
bladder cancer (continued). "Further studies have reported that p38MAPK and MK2 regulate the invasion and metastasis of bladder cancer through MMP-2 and MMP-9 mRNA stability modulation." (PMID 30850014, 2019). "Taken together, it can be concluded that the invasion of bladder cancer cells is regulated by p38MAPK-driven MK2 through stabilization of MMP-2/9 transcripts." (PMID 30850014, 2019). "Honokiol reduced steroid receptor coactivator-3 (SRC-3), matrix metalloproteinase (MMP)-2, and Twist1, preventing the invasion of urinary bladder cancer cells." (PMID 31877856, 2019). "It was demonstrated that loss of miRNA-141 and miRNA-200b expression increases the invasion and migration capacities of bladder cancer cell lines and up regulates MMP-2, MMP-9, vimentin, N-cadherin while down regulates E-cadherin expression." (PMID 30544619, 2018). "Contradictory results have been reported in previous studies about the prognostic value of MMP2 in bladder cancer." (PMID 28427222, 2017). "Recent data indicate that p38 MAPK-driven MAPKAPK2 regulates the invasion of bladder cancer by modulating MMP-2 and MMP-9 activities." (PMID 28678918, 2017). "The labels mean the genes VEGFA, MMP2 and MDM2 from the target gene set of the cancers (C) associated co-function module can be mapped to the Bladder cancer pathway." (PMID 28340554, 2017). "Our most recent studies also demonstrate that RhoGDIβ functions as a downstream mediator of XIAP and mediates matrix metalloproteinase (MMP)‐2 expression, which positively regulates bladder cancer invasion (H. Jin and C. Huang, unpublished data)." (PMID 28846829, 2017). "Here, we further reveal that Sp1 bound directly to the mmp‐2 promoter and increased its transcription, promoting bladder cancer cell invasion." (PMID 28846829, 2017). "In our analysis of a publicly available database, it was suggested that ANG and MMP2 genes are amplified in a subset of bladder cancers." (PMID 27317771, 2016). "Our results indicate that the ANG gene is amplified in human bladder cancer, leading to reduced expression of DNMT3b and increased expression of MMP2." (PMID 27317771, 2016). "The results suggest that the MMP2 gene is amplified in ANG-overexpressing bladder cancer cells, supporting ANG's oncogenic characteristics." (PMID 27317771, 2016). "Mean relative mRNA levels for both ANG and MMP2 in muscle invasive bladder cancer were significantly elevated compared to the mean relative mRNA levels for ANG and MMP2 in non-muscle invasive bladder cancer, thus confirming our results." (PMID 27317771, 2016). "We first analyzed ANG, DNMT3b and MMP2 mRNA levels in human bladder cancer tissues by quantitative RT-PCR." (PMID 27317771, 2016). "To further define the role of ANG, DNMT3b and MMP2 in tumorigenesis, we collected 78 fresh bladder cancer samples from bladder cancer patients and extracted DNA and RNA for analysis." (PMID 27317771, 2016). "Zymographic analysis of the expression levels of MMP-9 and active MMP-2 demonstrated a proportional increase with tumor grade and invasiveness in bladder cancer." (PMID 25621068, 2015). "A previous study found that MMP2 was downregulated by treatment with cantharidin in bladder carcinoma cells." (PMID 26135631, 2015). "The p38 MAPK was activated during the log phase growth of bladder cancer cells and regulated invasion of bladder cancer by modulation of MMP-2 and MMP-9 expression and activity." (PMID 26312564, 2015). "Elevation of MMP2 has been reported in several cancer tissue types including breast, lung, gastric, ovarian, and bladder cancers." (PMID 26307680, 2015). "In the current study, ELK1 silencing in AR-positive bladder cancer lines cultured with androgen resulted in significant decreases in cell migration and invasion as well as the expression and enzymatic activity of MMP-2/MMP-9." (PMID 26342199, 2015). "GRP170 in bladder cancer cells was also found to chaperone matrix metalloproteinase-2 (MMP-2) for secretion, thereby promoting tumor invasion." (PMID 25629003, 2014).
bladder cancer (continued). "The polymorphisms of MMP-1-1607 1G/2G, MMP-2-1306 C/T, and MMP-9-1562 C/T were reported to be related with bladder cancer susceptibility, but the conclusions remain to be inconsistent." (PMID 24390660, 2014). "p38-MAPK can regulate invasion by modulation of MMP-2/-9 mRNA level and zymographic activity in bladder cancer model." (PMID 23710144, 2013). "Taken together, our study detected many species of gelatinases in the urine of bladder cancer patients with primary tumor (both bilharzial and non bilharzial) including MMP-2, MMP-9, MMP-9 dimer, MMP-9/NGAL, MMP-9/TIMP-1 and ADAMTS-7." (PMID 23672427, 2013). "As a result of these functions and roles, MMP2 is an extremely important protein in bladder cancer development and progression." (PMID 24223658, 2013). "In recent, p38 is implicating mediating bladder cancer invasion via regulation of MMP-2 and MMP-9 at the level of mRNA stability." (PMID 22454661, 2012). "MMP plays an important role in cancer invasion and metastasis and MMP-2 elevation in bladder cancer tissues has been reported to be correlated with tumor stage and poor prognosis in bladder cancer patients." (PMID 23226455, 2012). "Recent advances in cancer cell biology have led to the association of MMP-2 and MMP-9 expression in bladder cancer progression." (PMID 22962576, 2012). "In bladder cancer, both the expressions of MMP-2 and MMP-9 expression increase significantly as the tumor grade and stage increase, with the MMP-2 expression increasing significantly as the grade and stage increase." (PMID 21941546, 2011). "Wnt/frizzled signaling is also known to stimulate cellular production of specific gelatinases including MMP2 which has been implicated in HB-EGF activation and cleavage as well as the progression and/or occurrence of various cancers including bladder cancer." (PMID 21143984, 2010). "The 5-year survival rate for patients with bladder cancer was significantly lower in the MMP2 positive group." (PMID 16901349, 2006). "It has been described in the literature that elevated expressions of MMP2 and MMP9 in bladder cancer tissue at the mRNA and protein level are associated with advanced tumour stage, grade, and a decreased survival rate." (PMID 16901349, 2006). "The expression of MMP2 changes during the development of bladder cancer." (PMID 41228251, 2025). "This study specifically utilized RT4 cells, a well-characterized, non-invasive bladder cancer model, to investigate the impact of proTAME, cisplatin, and gemcitabine on MMP2/MMP9-mediated migration, establishing a foundation for subsequent research using more aggressive bladder cancer models." (PMID 40136519, 2025). "Previous studies had demonstrated that miR-130b-3p could modulate the expression of MMP2, thereby regulating the proliferation, migration, and invasion of bladder cancer cells." (PMID 40593236, 2025). "Moreover, miR-146b overexpression promotes the invasion ability of human bladder cancer by increasing MMP2 protein expression." (PMID 40224178, 2025). "We found that knockdown of MMP-2 inhibited the ability of bladder cancer cells to invade in vitro." (PMID 40133252, 2025). "We identified an XIAP/YTHDC1/MMP-2 pathway that promotes metastasis of bladder cancer." (PMID 40133252, 2025). "Our findings are consistent with a study reported on human bladder cancer cells, where treatment with varying concentrations of NaHS (exogenous H2S donor) led to a significant increase in the expression levels of MMP-2 and MMP-9, along with enhanced invasion capacity." (PMID 41583211, 2025). "In our study, we have found that MMP-2 genes were downregulated in diabetic cardiopathy I, proteoglycans in cancer, estrogen signaling, fluid shear stress and atherosclerosis, relaxing signaling, bladder cancer, and GnRH signaling pathways." (PMID 40427657, 2025).
bladder cancer (continued). "Here, we reported that hAM preparations (homogenate and extract) inhibited the expression of the epithelial–mesenchymal transition markers N-cadherin and MMP-2 in bladder cancer urothelial cells in a dose-dependent manner, while increasing the secretion of TIMP-2." (PMID 37932474, 2023). "However, the target mRNAs of NCL in bladder cancer, such as Rho factor and/or MMP-2, are also diverse." (PMID 36831493, 2023). "We found that the protein level of MMP9 was unchanged, while TRIM9 overexpression facilitated MMP2 production in Biu-87/T24 cells, and blockade of Smad2/3 signaling suppressed MMP2 expression, indicating that Smad2/3 mediated downstream MMP2 production in bladder cancer cells." (PMID 37249822, 2023). "The LG urinary bladder cancer tissue demonstrated an increase in the actual activity of MMP-2." (PMID 36979935, 2023). "In addition, the inhibition of Dicer expression enhanced the mesenchymal phenotype and promoted bladder cancer cell invasion by suppressing MMP-2 expression." (PMID 35951366, 2022). "Furthermore, compared with previous studies, our study included more studies and variants, and then it was revealed that MMP-2 rs243865 was associated with NPC and PCa risk, and MMP-7 rs11568818 with bladder cancer, CC, and CRC risk." (PMID 35574300, 2022). "In addition, baicalin inhibits bladder cancer cell invasion by attenuating matrix metallopeptidases (MMPs) levels including MMP-9 and MMP-2 in bladder carcinoma 5637 cells." (PMID 33996570, 2021). "Moreover, induction of IL-8 secretion was associated with higher levels of MMP-2 and MMP-9 activity in endothelial cell and bladder cancer models." (PMID 34066355, 2021). "For example, XIAP could increase MMP2 level to facilitate the progression of bladder cancer; moreover, XIAP also promotes the migration of esophageal cancer cells by enhancing epithelial–mesenchymal transition." (PMID 34650909, 2021). "Studies have shown that bladder cancer invasion may be promoted by the p38 MAPK pathway through the regulation of the downstream MAPKAPK2 so as to regulate MMP-2 and MMP-9 activity." (PMID 29794990, 2018). "In conclusion, this study demonstrated that flaccidoxide-13-acetate inhibits the migration and invasion of T24 and RT4 bladder cancer cells through the down-regulation of MMP-2 and MMP-9 expressions, and the process is controlled by the FAK/PI3K/AKT/mTOR pathway." (PMID 29280977, 2017). "Interestingly, expression of ANG, DNMT3b and MMP2 is correlated with disease free survival in human bladder cancer." (PMID 27317771, 2016). "Taken together, our study unravels an inverse relationship between cell migration and invasion in human bladder cancer T24T cells and suggests a novel mechanism underlying the divergent roles of SOD2 and MMP-2 in regulating metastatic behaviors of human bladder T24T in cell migration and invasion." (PMID 25402510, 2015). "Furthermore, a recent study using 5637 bladder cancer cells transfected with rat TRPV2 cDNA, showed that TRPV2 overexpression enhanced bladder cancer cell migration and invasion by direct matrix metalloproteinase 2 (MMP2) regulation." (PMID 24709905, 2014). "In the current study, a total of five case–control studies with 1,141 cases and 1,069 controls were included in the meta-analysis, and the association between MMP-1-1607 1G/2G, MMP-2-1306 C/T, and MMP-9-1562 C/T polymorphisms and bladder cancer risk was explored." (PMID 24390660, 2014). "Different independent studies consistently reported elevated MMP-2 activity in urine samples from bladder cancer as compared to normal healthy subjects, which confirm our results and raise the hope HMW MMPS can be used as a diagnostic biomarker for this malignancy." (PMID 23672427, 2013). "The purpose of this study was to investigate whether the expression of MMP-9, MMP-2 and its specific inhibitors, are expressed in a reproducible, specific pattern and if the profiles are related to prognosis in Bladder Cancer (BC)." (PMID 22695075, 2012).
bladder cancer (continued). "The results demonstrated that MMP-2 protein overexpression may be an independent prognostic biomarker for bladder cancer progression." (PMID 22852097, 2012). "A recent report indicated that MAPKAPK2 could mediate p38 mitogen-activated protein kinase (MAPK) activation to drive invasion of bladder cancer by inducing the expression of MMP-2 and MMP-9." (PMID 22140479, 2011). "The median value for MMP2 mRNA expression in the bladder cancer samples was 0.038." (PMID 21483670, 2011). "Tissue inhibitor of metalloproteinase 2 and MMP2 have also been investigated in bladder cancer." (PMID 15083203, 2004). "A significant correlation with MMP-2 gene expression implies that the regulation of MMP-2 may be a possible mechanism underlying the effect of SPARC on the progression of oesophageal and bladder cancer." (PMID 15558074, 2004). "In addition, TGF-β induced MMPs expression has been shown to enhance the invasion and migration capabilities of various cancer cells, and our study also identified an increased MMP2 expression in the CEACAM6/Smad2/3 signaling medicated bladder cancer progression." (PMID 37249822, 2023). "It suggests that pro-MMP-2 may be taken into consideration as a bladder cancer marker." (PMID 36979935, 2023). "Another group further confirmed the association of MK2 with MMP2 by transfecting cancer cells with constitutively active MK2, demonstrating that this was associated with high MMP2 activity, and one more study also suggested that MK2 is associated with MMP2 and MMP9 activity in bladder cancer." (PMID 36558958, 2022). "In addition, in the current study, it can be seen that MMP-2 rs243865 was not obviously related to the risk of certain cancer types in three models, such as BC, bladder cancer, CRC, GC, oral cancer, and lymphoma." (PMID 35574300, 2022). "Similarly, the researchers attenuated the proliferation and migration of bladder cancer cells through GPNMB gene knockout while reducing the expression of MMP-2, MMP-9, and β-catenin and demonstrated that high GPNMB expression is a risk factor for bladder cancer." (PMID 36090016, 2022). "Therefore, urinary levels of MMP-2 could serve as a potential supportive biomarker for the diagnosis and monitoring of the patients with bladder cancer." (PMID 32751899, 2020). "Hence it could be said that active p38MAPK signaling by modulation of MMP-2/9 activity may regulate the migration/invasion in bladder cancer." (PMID 30850014, 2019). "Our most recent studies demonstrate that RhoGDIβ is able to promote human bladder cancer (BC) invasion and metastasis in an X‐link inhibitor of apoptosis protein‐dependent fashion accompanied by increased levels of matrix metalloproteinase (MMP)‐2 protein expression." (PMID 28846829, 2017). "In addition to these bladder cancer cell lines, MMP2 gene amplification may occur in bladder tumors with high ANG levels." (PMID 27317771, 2016). "Thus, it is tempting to speculate that the adverse expression of ANG-DNMT3b-MMP2 may be utilized as a prognostic factor for human bladder cancer." (PMID 27317771, 2016). "Thus, the survival analysis further suggests the ANG-DNMT3b-MMP2 axis play a role in bladder cancer progression and thus could hold promise as prognostic markers." (PMID 27317771, 2016). "Furthermore, we demonstrated miR-124-3p could inhibit bladder cancer cell epithelial mesenchymal transfer, and regulated the expression of c-Met, MMP2, MMP9." (PMID 24180482, 2013). "Our functional studies have shown that XIAP upregulated expression of MMP-2 by downregulating YTHDC1 and promoting metastasis of bladder cancer cells." (PMID 40133252, 2025). "Melatonin inhibits bladder cancer cell migration and invasion by downregulating ZNF746-regulated MMP-9/MMP-2 signaling." (PMID 40756978, 2025).